BRAF (B-Raf proto-oncogene, serine/threonine kinase)
Diseases named in the same sentence as BRAF in open-access papers (continued):
Sharing a sentence is not in itself a finding about the gene and the disease.
glioma (447 papers, 2009 to 2026). A benign or malignant brain and spinal cord tumor that arises from glial cells (astrocytes, oligodendrocytes, ependymal cells). "In high-grade gliomas with a defined mutation (e.g., BRAF mutation, EGFR mutation), patients receiving targeted therapy (tyrosine kinase inhibitor) had a higher overall survival (OS) rate compared to those receiving conventional chemotherapy." (PMID 41596345, 2026). "BRAF mutation is clinically important since one of the main characteristics of gliomas harboring BRAF V600E mutations is poor response to the conventional chemotherapy and the risk of transforming to high-grade gliomas." (PMID 41596345, 2026). "As in other CNS low-grade gliomas, BRAF alterations (mutation and fusion) are most commonly seen as molecular aberration in thalamic LGGs." (PMID 41596345, 2026). "With the recent progress of molecular analysis, KRAS G12R, BRAF V600E mutation, and KIAA1549::BRAF fusion were identified in TG, and the DNA methylation profile of TG suggests its classification as a distinct entity from other lower grade glioma (LrGG)s." (PMID 39432011, 2025). "Other pHGG subtypes include those that are ACVR1-mutant, histone wild-type, such as pleomorphic xanthoastrocytoma (PXA)-like gliomas enriched with BRAF mutations, and NF1-associated gliomas with receptor tyrosine kinase fusions." (PMID 40647519, 2025). "Homozygous deletions of CDKN2A, the gene that codes for P16, result in unregulated cell division through disinhibition of CDK4/6 and have been implicated in multiple cancer types, including in BRAF V600E gliomas." (PMID 40094009, 2025). "Pleomorphic xanthoastrocytoma (PXA) is a rare, localized glioma characterized by frequent BRAF V600E mutations and CDKN2A/B deletions." (PMID 40231261, 2025). "Another study (NCT04201457) is exploring the use of hydroxychloroquine in combination with trametinib (for BRAF fusion or NF-1 associated glioma) or with trametinib and dabrafenib (for BRAFp.V600E) in recurrent pLGGs or pHGGs)." (PMID 40422539, 2025). "BRAF fusions are observed predominantly in pediatric-type gliomas and are associated with MAPK pathway activation." (PMID 40647519, 2025). "For example, gliomas harboring BRAF alterations, including fusions and V600E mutations, exhibit distinct biological behaviors." (PMID 40647519, 2025). "Tovorafenib: Tovorafenib is a type II RAF inhibitor, which was approved by the FDA in 2024 for children 6 months and older with relapsed/refractory low-grade gliomas harboring BRAF V600E mutations or fusions." (PMID 40867225, 2025). "The BRAF inhibitor dabrafenib has exhibited significant clinical efficacy in paediatric patients with BRAF V600 mutation‐positive low‐grade glioma and high‐grade glioma." (PMID 40662483, 2025). "In conclusion, this case illustrates the value of personalized, molecularly driven treatment in pediatric low‐grade gliomas with rare BRAF mutations." (PMID 40765221, 2025). "In a clinical trial involving gliomas with the BRAF-V600E mutation, the BRAF inhibitor dabrafenib (NCT01677741) demonstrated significant clinical activity and was well tolerated in patients with this mutation." (PMID 40113789, 2025). "Particularly, BRAF mutations have been found in various human tumors including CNS tumors (e.g., low- and high-grade pediatric glioma)." (PMID 40175630, 2025). "Studies in mice indicate that while a KIAA1549::BRAF fusion is sufficient to generate glioma-like lesions, this is associated with increased Iba1+ microglia infiltration and is inhibited if Ccr2-mediated microglial recruitment is blocked." (PMID 39948623, 2025). "Using RCAS/t-va murine models with PDGFb and BRAF V600E mutations, we identified distinct lncRNA signatures associated with the immunosuppressive and pro-inflammatory milieus of gliomas." (PMID 40527978, 2025). "BRAF mutations currently carry an uncertain prognostic weight in high grade gliomas, yet they are a significant feature if present as they are a targetable mutation." (PMID 40270074, 2025).
glioma (continued). "For instance, in gliomas, BRAF fusion variants have been found to cause complex structural rearrangements (e.g., selective splicing, frameshift rearrangements), potentially promoting phenotypic transformation of tumor cells." (PMID 40896440, 2025). "For example, it was shown that despite a BRAF-amplified glioma harboring IDH1/2 and ATRX mutations, known for a better prognosis, a reduced survival was observed vs. V600E mutation v-Raf murine sarcoma viral oncogene homolog B1 BRAFv600E." (PMID 40560010, 2025). "It is known that BRAF gene mutation plays an important role in the occurrence and development of some gliomas." (PMID 40535548, 2025). "Class I BRAF mutations account for 44–66% of all BRAF mutations in gliomas, with class II and III mutations making up 10–24% and 4–10%, respectively." (PMID 40332392, 2025). "Only a few formal clinical trials have been conducted in pediatric oncology, including trametinib plus dabrafenib (a RAF inhibitor) in glioma with BRAF V600 variants, and stand-alone trametinib in refractory juvenile myelomonocytic leukemia." (PMID 40041314, 2025). "Central nervous system tumors: In central nervous system (CNS) tumors, BRAF mutations occur in about 7% of cases." (PMID 40332392, 2025). "Currently, there are limited data on the duration of treatment and outcomes once targeted therapy is discontinued for patients with gliomas and the BRAF V600E mutation." (PMID 39057171, 2024). "Trametinib is a MEK1/2 inhibitor that has been found to be effective for treatment of BRAF V600E-mutated gliomas, and it is also being tested in the treatment of patients with NF1 mutations." (PMID 39684714, 2024). "In the Rare Oncology Agnostic Research (ROAR) study, BRAFi dabrafenib with or without trametinib (a MEK inhibitor, MEKi) was evaluated in 45 patients with BRAF-mutated high-grade glioma (HGG, 31 diagnosed as GBM)." (PMID 39408897, 2024). "This review aims to evaluate the efficacy and safety of combination therapies, particularly Dabrafenib and Trametinib, in pediatric gliomas with BRAF V600 mutations and discusses their potential in improving clinical outcomes." (PMID 39654184, 2024). "In a basket trial (NCT01524978), the BRAFi vemurafenib was associated with partial response (PR) in 1/11 and stable disease (SD) in 5/11 treated patients with BRAF-mutated glioma." (PMID 39408897, 2024). "A pioneering Phase I/II clinical trial, initiated in 2020, is investigating the combined efficacy of dabrafenib, trametinib, and hydroxychloroquine in the treatment of recurrent gliomas characterized by BRAF mutations." (PMID 39184045, 2024). "Gliomas are tumors arising in the central nervous system, frequently associated with Class I mutations and BRAF fusions." (PMID 39654184, 2024). "Reports for patients with gliomas also identified predictive alterations in IDH1 (19.0%) or BRAF (V600E mutation 3.4%, fusion 2.8%)." (PMID 37682776, 2024). "Promising targeted therapies for gliomas with the BRAF V600E mutation include BRAF inhibitors such as Vemurafenib and Dabrafenib, as well as combinations of BRAF and MEK inhibitors." (PMID 39201639, 2024). "Targeted agents like dasatinib for BCR::ABL1 ALL, selumetinib for BRAF mutant gliomas, and PARP inhibitors for cancers with loss of homologous repair showed activity in relevant pediatric preclinical models." (PMID 39510293, 2024). "Two trials were mutation-specific; one focused on IDH1-R132H Grade 2 glioma, while the other mutation-specific trial included tumors that had a BRAF-V600E mutation (NCT02034110)." (PMID 39337916, 2024).
glioma (continued). "In pediatric patients, dabrafenib specifically targets abnormal BRAF proteins, particularly the BRAF V600E mutation, which is common in pediatric low-grade gliomas." (PMID 39654184, 2024). "Pleomorphic xanthoastrocytoma (PXA) is a rare pediatric low-grade glioma (pLGG), of which 60%-80% exhibit the BRAF V600E mutation, that enhances the aggressiveness and progression to an eventual pediatric high-grade glioma (pHGG)." (PMID 39188362, 2024). "The treatment of BRAF V600E mutated gliomas with BRAFis and MEKis is being increasingly integrated into the clinical practice for PLGG and pediatric HGG." (PMID 39057171, 2024). "This review aims to address these gaps by analyzing recent clinical trials, evaluating the implications of resistance mechanisms, and exploring emerging therapies and future directions in the management of pediatric gliomas with BRAF mutations." (PMID 39654184, 2024). "This study showed that after treated with dabrafenib combined with trametinib, the rates of AEs and death events in BRAF V600 mutation-positive glioma were 50% and 43%, respectively." (PMID 39172230, 2024). "BRAF has been reported to occur in various gliomas, and EGFR is one of the diagnostic indicators of grade 4 GBM of the WHO." (PMID 39771050, 2024). "In pediatric populations, particularly those with gliomas harboring BRAF mutations, the safety and tolerability of combination therapy must be carefully considered due to differences in drug metabolism and side effect profiles compared to adults." (PMID 39654184, 2024). "Trial Design: Enrolled 41 patients with BRAF-mutated pediatric high-grade gliomas (pHGG) across 28 sites in 13 countries from December 2017 to August 2020." (PMID 39654184, 2024). "The consensus was to taper MEKis first given the fact that gliomas with the BRAF V600E mutation can be treated effectively with BRAFi monotherapy." (PMID 39057171, 2024). "Given that no clinical trial is currently prepared to address these specific and critical questions, we developed a Canadian Consensus for the Treatment of BRAF V600E Mutated Pediatric Gliomas." (PMID 39057171, 2024). "The combination of Dabrafenib and Trametinib offers a targeted treatment specifically for pediatric gliomas with BRAF V600 mutations." (PMID 39654184, 2024). "By focusing on these aspects, the integration of precision medicine and pharmacogenomics into treatment paradigms for pediatric gliomas with BRAF mutations can significantly transform clinical practice and improve patient outcomes." (PMID 39654184, 2024). "Recent research has suggested a potential role for BRAF mutations in the pathogenesis of epilepsy in patients with gliomas." (PMID 39201639, 2024). "The BRAFV600E mutation is the most common BRAF mutation in primary brain tumors and has been found in adult and pediatric gliomas, Dabrafenib, an effective BRAFV600 inhibitor, has shown therapeutic effects on BRAFV600-mutated pediatric gliomas." (PMID 38937742, 2024). "High-grade gliomas, including classic GB, seldom have BRAF mutations and yield poor therapeutic outcome due to the low mutation rate." (PMID 39107839, 2024). "In conclusion, the emerging paradigm of molecularly targeted therapies, particularly the combination of Dabrafenib and Trametinib, has revolutionized the treatment landscape for pediatric gliomas with BRAF mutations." (PMID 39654184, 2024). "Recent developments in molecularly targeted therapies for pediatric gliomas with BRAF mutations have highlighted several promising avenues." (PMID 39654184, 2024). "Our results showed that PR, CR, ORR, and RR of dabrafenib combined with trametinib in BRAF V600 mutation-positive glioma were, 30%, 18%, 39%, and 58%, respectively." (PMID 39172230, 2024). "Class I BRAF mutations represent 44–66% of all BRAF mutations in gliomas, while class II and III mutations represent 10–24% and 4–10%, respectively." (PMID 38203795, 2024).
glioma (continued). "Dabrafenib and Trametinib offer a promising targeted therapy for juvenile gliomas with BRAF V600 mutations, with better survival outcomes and manageable safety profiles." (PMID 39654184, 2024). "The meta-analysis, which included a comprehensive collection of 8 studies, revealed the effects of dabrafenib combined with trametinib in BRAF V600 mutation-positive glioma." (PMID 39172230, 2024). "Recent clinical trials have established the efficacy and safety of BRAF-targeted therapies for treating pediatric gliomas with BRAF mutations." (PMID 39654184, 2024). "It had potential for use in patients with BRAFV600-mutated tumors, especially primary CNS cancers, and patients with refractory prior BRAF/MEK inhibitors." (PMID 38203795, 2024). "BRAF inhibitors (BRAFi) are widely utilized in targeting the BRAF V600E mutation in non-CNS cancers." (PMID 39408897, 2024). "Two BRAF-rearranged gliomas had TERT promoter mutations and five had loss of CDKN2A/B, all of which were grade 4." (PMID 36854806, 2023). "This review is an attempt to provide comprehensive information regarding molecular alterations related to the aggressiveness modulation in BRAF-mutated gliomas and the current knowledge on how to use those targeted therapies in such situations." (PMID 36831610, 2023). "There is only one ongoing clinical trial investigating the efficacy of encorafenib/binimetinib in recurrent BRAF V600E/K-mutated glioma patients (NCT03973918)." (PMID 37857607, 2023). "Recent studies have shown that the low-grade gliomas with BRAF mutations have been frequently accompanied by epileptic seizures." (PMID 36763212, 2023). "The other proliferative factors, regularly deregulated in adult and pediatric HGGs (e.g., MYC, MDM4, CDK1), were rarely studied in BRAF p.V600E mutated gliomas, but their paired genes can exhibit high level of amplifications." (PMID 36831610, 2023). "In the central nervous system, BRAF mutations are usually found in gliomas, such as the pilocytic astrocytomas, diffuse midline gliomas, and in high grade astrocytomas with piloid features." (PMID 36763212, 2023). "Pediatric gliomas, on the other hand, are frequently associated with genetic alterations such as BRAF fusion or mutation, KIAA1549-BRAF fusion, and mutations in H3F3A or HIST1H3B." (PMID 37444408, 2023). "Among adult patients with BRAF V600E mutated brain tumors, 15 of the 31 high-grade glioma patients had an objective response rate (ORR) of 33% with 3 Complete Responses (CR) and 12 PRs while the duration of response among all high-grade tumors was 13.6 months." (PMID 37231247, 2023). "Regarding MAPK-altered high-grade gliomas and compared to histone-mutated tumors, BRAF p.V600E mutation drives a better prognosis connecting those malignant forms to specific high-grade genotypes and immune microenvironments." (PMID 36831610, 2023). "BRAF V600E mutations are more commonly associated with other IDH-wt gliomas, such as circumscribed neuroepithelioid tumors, ganglioglioma, pleomorphic xanthoastrocytoma (PXA), and pilocytic astrocytoma." (PMID 37568598, 2023). "The BRAF p.V600E variants were more frequently detected in pLGGs that transform into high-grade gliomas." (PMID 37397394, 2023). "Other genomic alterations observed within functional classes were consistent with the putative roles of those BRAF mutation classes in glioma pathogenesis." (PMID 36854806, 2023). "We propose that, in depolarized glioma cells with BRAF mutations, high KCNMA1 levels act to repolarize membrane potential and facilitate cell growth." (PMID 36763212, 2023). "Gliomas with BRAF gains (Cluster 2) were more closely associated with one another than gliomas with BRAF Class I–III mutations or fusions." (PMID 36854806, 2023). "Ongoing clinical trials are investigating the use of the dual combination of BRAFi and MEK inhibitors (MEKi) to treat BRAF p.V600 mutation-positive gliomas." (PMID 37397394, 2023).
glioma (continued). "BRAF mutations have been found in gliomas which exhibit abnormal electrophysiological activities, implying their potential links with the ion channel functions." (PMID 36763212, 2023). "Conversely, other studies have shown BRAF induction in human PA-associated glioma stem cells to lead to OIS." (PMID 37124503, 2023). "The Drosophila RafGOF tumor model mimics gliomas that carries BRAF mutations and show corresponding phenotypes such as glial cell over-proliferation, seizure-like behavior, and shortened life span." (PMID 36763212, 2023). "This enables investigation of the tumor cell of origin after BRAFV600E mutation, as well as the role of BRAF in glioma development." (PMID 37920169, 2023). "Nevertheless, the cellular origin of BRAF-mutated gliomas remains underappreciated, and further studies are required to understand the cellular and molecular mechanisms underlying the development of these tumors." (PMID 37920169, 2023). "For instance, specific BRAF alterations (mutations and fusions) in pediatric-type gliomas and neurotrophic receptor tyrosine kinase (NTRK) family alterations in infant-type hemispheric gliomas can be targeted with molecularly tailored therapies." (PMID 38157879, 2023). "Firstly, BRAF-V600E mutations (valine substituted with glutamic acid at position 600) are present in gliomas including pleomorphic xanthoastrocytoma, ganglioglioma, pilocytic astrocytoma, low-grade gliomas and pediatric GBM." (PMID 37182181, 2023). "Mutations in KRAS, HRAS and NRAS are known in gliomas and are often concomitant with BRAF mutations and fusions." (PMID 37490467, 2023). "The IDH mutation presents a rational target for small molecule inhibition and immune therapy in diffuse astrocytomas and oligodendrogliomas, while the BRAF pathway is frequently mutated and treatable in circumscribed gliomas." (PMID 36566461, 2023). "A patient with a BRAF V600E mutation in a high‐grade glioma originating from ganglioneuroma was treated with dabrafenib (a selective inhibitor of BRAF V600E) and TTFields after the failure of TMZ‐based therapy." (PMID 36987739, 2023). "This review aims to provide comprehensive data about the role of the MAPK pathway, focusing on BRAF gene mutation, its involvement in the glioma tumor initiation, prognosis, progression, and treatment." (PMID 36831610, 2023). "Excitement grew when early reports showed BRAF mutations occurred in glioma, given the successes of targeting this molecule in other diseases." (PMID 37124503, 2023). "BRAF mutations were identified in various cancers including 59% in melanomas, 18% in colorectal cancers, 11% in gliomas, and 14% in liver cancers." (PMID 37182181, 2023). "Here, we characterize a multi-institutional cohort of more than 300 patients (>200 adults) with BRAF-mutated glioma using clinical, pathological/molecular, and outcome data." (PMID 36854806, 2023). "BRAF V600E mutations, although rare (2% to 8%), can be detected in all grades of adult infiltrative gliomas." (PMID 37124503, 2023). "BRAF is the most commonly altered molecular driver in pediatric low-grade gliomas, with BRAF V600E mutations being more frequent in pleomorphic xanthoastrocytoma (PXA) and ganglioglioma (GG)." (PMID 37108511, 2023). "Our study provides a new strategy to antagonize the progression of gliomas as induced by BRAF mutations." (PMID 36763212, 2023). "In this study, we retrospectively characterize a large multi-institutional cohort of adults with BRAF-mutated gliomas." (PMID 36854806, 2023). "Recently, in a small study it was possible to detect a BRAF V600E mutation in the plasma of 4/5 patients with BRAF V600E mutant brain tumors (both gliomas and brain metastasis) confirmed by ddPCR assay." (PMID 37542343, 2023).